TRPV1 (transient receptor potential cation channel subfamily V member 1)
Diseases named in the same sentence as TRPV1 in open-access papers (continued):
Sharing a sentence is not in itself a finding about the gene and the disease.
Obesity (continued). "Capsaicin (CAP) has an anti-obesity effect that has been shown to involve the transient receptor potential vanilloid-1 (TRPV1) channel." (PMID 32180694, 2020). "Overall, the existing data suggest that TRPV1 plays divergent roles in BAT and WAT adipogenesis to promote BAT-mediated thermogenesis and counteract WAT-associated obesity." (PMID 33613196, 2020). "In the past years, TRPV1 has been studied for its involvement in adipocyte differentiation and energy metabolism, which further related to obesity management." (PMID 32175809, 2020). "TRPV3 often form functional heteromeric channels with TRPV1, which also shows similar effects in regulating adipogenesis and obesity with TRPV1." (PMID 32175809, 2020). "In BAT, TRPV1 activation is involved in the stimulation of metabolism and energy expenditure to protect against obesity." (PMID 32175809, 2020). "Capsaicin (CAP) activates transient receptor potential vanilloid subfamily 1 (TRPV1) to counter high-fat diet (HFD)-induced obesity." (PMID 31197191, 2019). "Thirdly, the long-terms effects of TRPV1 antagonist administration need to be investigated both for beneficial actions (for example, reduced CVD risk, including obesity-induced hypertension) and adverse effects such as impaired noxious heat perception)." (PMID 31344877, 2019). "Previous research works have shown that TRPV1 activation by CAP is important for its anti-obesity action." (PMID 31197191, 2019). "However, the role of TRPV1 in obesity and associated side effects—especially dysregulation of glucose homeostasis—is complex, as indicated by contrasting results from Trpv1−/− mice in diet-induced obesity, in which both beneficial and detrimental effects have been observed." (PMID 31434293, 2019). "There is good experimental evidence that T2DM (along with obesity) has a low-grade inflammatory component, maintained at least in part by TRPV1-expressing sensory neurons." (PMID 31344877, 2019). "Capsaicin, an agonist of TRPV1, has an anti-obesity effect in rodents and reduces food intake in humans." (PMID 30108548, 2018). "Deletion of TRPV1 has further raised the profile of this receptor in treating obesity as the deletion exacerbated diet-induced obesity and insulin resistance." (PMID 29772784, 2018). "The levels of TRPV1 mRNA in BAT and WAT are reduced in HFD-induced obesity and leptin receptor deficient mice suggesting possible involvement in the development of obesity." (PMID 30108548, 2018). "This suggests that disrupted TRPV1 signaling plays a role in the dampened vagal afferent signaling observed in high fat diet-induced obesity, however, this requires further investigation." (PMID 30108548, 2018). "Further, these effects of TRPV1 on SNS activity are lost in obese subjects suggesting TRPV1 dysfunction in obesity." (PMID 30108548, 2018). "Among these studies, dietary capsaicin has been recognized to exert a beneficial effect on preventing obesity and to improve glucose homeostasis by activation of TRPV1." (PMID 28890700, 2017). "Activation of TRP vanilloid type 1 (TRPV1) appears to stimulate cellular mechanisms against obesity, by altering mediators of lipid catabolism and thermogenesis." (PMID 28068423, 2017). "TRPV1 was deemed as a potential target for the prevention of obesity due to its effect on energy metabolism and balance." (PMID 28424369, 2017). "The anti-obesity effect of CAP via TRPV1 activation has been extensively studied, but the impact of CAP on gut microbiota has not been well studied." (PMID 28280490, 2017). "Capsaicin is a worldwide consumed ingredient from chili peppers, and its anti-obesity function has been extensively studied through activation of TRPV1 channel." (PMID 28280490, 2017). "Consistent with the human data on the other hand, capsaicin consumption was shown to induce browning of white adipose tissue and reduce obesity in mice in a TRPV1 dependent fashion." (PMID 27563913, 2016).
Obesity (continued). "Mounting evidence indicates that TRPV1 activation by capsaicin is beneficial for the management of obesity, diabetes mellitus, cardiovascular diseases, various cancers, dermatological conditions, and neurogenic bladder." (PMID 27120617, 2016). "TRPV1 was shown to be a potential target for the prevention of obesity because of its effect on energy balance." (PMID 27120617, 2016). "Activation of TRPV1 channels by capsaicin prevented adipogenesis and obesity and nonalcoholic fatty liver disease." (PMID 25849380, 2015). "The mechanosensitivity of gastric mucosal receptors was unaffected by HFD-induced obesity and/or TRPV1 channel disruption." (PMID 26285043, 2015). "TRPV1-evoked alterations in Cx43-mediated adipocyte-to-adipocyte communication play an important role in obesity." (PMID 25849380, 2015). "Our previous studies showed that activation of TRPV1 by dietary capsaicin prevents obesity by inhibiting adipocyte differentiation and maturation with an increase in the induction of Ca2+ influx." (PMID 25849380, 2015). "Mice fed a diet with 49% energy from fat (ingredients unreported) and treated with the TRPV1 agonist capsaicin were found to be resistant to obesity." (PMID 26285043, 2015). "Overall, these data support a role of TRPV1 in the control of diabetes, insulin resistance and obesity." (PMID 24861977, 2014). "As well, inactivation of TRPV1 accelerates the development of metabolic disorders such as hypertension, atherosclerosis, obesity, and fatty liver, whereas TRPV1 agonist activation protects against these metabolic diseases." (PMID 23878415, 2013). "Decreased cannabinoid receptors expression, increased anandamide degradation, decreased AMPK/eNOS activity as well as impairment of the response mediated by TRPV1 activation seem to contribute to reduce responses to cannabinoid agonists in obesity." (PMID 23667622, 2013). "TRPV1 is highly expressed in adipose tissue, where it is involved in processes related to adipogenesis, browning, and food intake, indicating its potential as a target for developing drugs for obesity control." (PMID 41346769, 2026). "Nevertheless, aberrant TRPV1 activation and expression may contribute to the onset and development of obesity." (PMID 40677717, 2025). "Targeting TRPV1 represents a potentially effective approach for managing obesity." (PMID 40677717, 2025). "Therefore, revealing the neuroendocrine regulatory mechanism of TRPV1 in obesity is particularly important." (PMID 40677717, 2025). "TRPV1 is expressed across the central nervous system and peripheral organs is involved in the regulation of hormone secretion, appetite and mitochondrial function, and is recognized as one of the key targets for preventing obesity." (PMID 40677717, 2025). "Therefore, age should be considered a potential influencing factor in the study of TRPV1 and obesity." (PMID 40677717, 2025). "Together, these approaches will help clarify whether CAP’s effects on MASLD stem from direct hepatic TRPV1 activation or result primarily from its systemic anti-obesity properties." (PMID 40864772, 2025). "Similarly, upregulation of TRPV1 inhibited adipogenesis in 3T3-L1 preadipocytes, and obesity was prevented in mice treated with fid TRPV1 agonists for 120 days compared with TRPV1-knockout mice." (PMID 41258240, 2025). "Chronic extensive pain is the main syndrome upsetting individuals with fibromyalgia (FM), accompanied by anxiety, obesity, sleep disturbances, and depression, Transient receptor potential vanilloid 1 (TRPV1) has been reported to transduce inflammatory and pain signals to the brain." (PMID 38164490, 2024). "Interestingly, it was found that capsaicin alleviated obesity and promoted white fat browning by activating the TRPV1." (PMID 38913071, 2024). "Taken together, these findings suggest that TRPV1-positive afferent renal nerves may have a protective role against obesity-induced renal injury and hypertension." (PMID 37047183, 2023).
Obesity (continued). "In addition, capsaicin and capsinoids prevent obesity by increasing energy expenditure and activating the TRPV1–sympathetic nervous system–BAT axis." (PMID 38084147, 2023). "Thus, capsaicin signaling in obesity and fat metabolism is mainly described as TRPV1-dependent, although some studies presented TRPV1-independent actions, including activation of PPARγ." (PMID 37892544, 2023). "In contrast, the removal of TRPV1 was reported to result in potent anti-obesity properties." (PMID 35164163, 2022). "The promotional effect of TRPV1 and UCP1 depletion on obesity and hypertension is associated with impaired energy expenditure and spontaneous activity, which might be a reflection of lower mitochondrial function." (PMID 35043013, 2022). "Therefore, TRPV1 has received a great attention as a potential target to treat different disorders including inflammation, obesity, hyperlipidemia and other metabolic diseases." (PMID 36589466, 2022). "TRPV1 protects the heart against cardiac dysfunction during endotoxemia which is used as a tool to induce or accelerate metabolic syndrome such as hyperlipidemia or obesity." (PMID 36589466, 2022). "It was found that knockout of TRPV1 protected against diet-induced obesity." (PMID 36589466, 2022). "Numerous studies highlighted that impaired signaling within TRPV1 may contribute to the development of various metabolic disorders, including obesity and T2DM." (PMID 35328503, 2022). "Consistently, our previous report also indicated that the inhibitory effect of TRPV1 on diet-induced obesity required higher BAT activity, which might affect the whole-body metabolic rate." (PMID 35043013, 2022). "The findings of in silico molecular studies of ginger compounds interacting with various receptors or proteins (e.g. β3-AR, TRPV1) are promising for the design of novel drugs/inhibitors in combating obesity, diabetes, inflammation, nausea, vomiting, and SARS-CoV-2." (PMID 34899343, 2021). "Besides, berberine alleviates olanzapine-induced obesity by targeting TRPV1/TRPV3 in hypothalamus of mice." (PMID 34249940, 2021). "All these studies indicate that the effects of TRPV1 on obesity are complex." (PMID 34345212, 2021). "If this conclusion is accurate, then it would indicate a possible target for future research on chronic treatment with TRPV1 agonists in the diabetic and obesity conditions, evaluating whether these agonists could attenuate or prevent vascular dysfunction." (PMID 33716794, 2021). "The function of sensory fibers containing TRPV1 is impaired in obesity, diabetes, and aging." (PMID 34149454, 2021). "A similar observation was confirmed for the TRPV receptor, where the authors evaluated the effect of capsaicin on the browning program in white adipose tissue (WAT) by the activation of TRPV1 channels to prevent diet-induced obesity in wild-type and TRPV1(-/-) mouse models." (PMID 33530406, 2021). "The function of sensory nerves, especially TRPV1-positive nerves, is impaired in obesity." (PMID 34069822, 2021). "Lacking TRPV1 exacerbates obesity and promotes insulin resistance, which is associated with diabetes and ageing." (PMID 32175809, 2020). "However, the anti-obesity effect of evodiamine was preserved after genetic ablation of TRPV1, suggesting a TRPV1-independent mechanism." (PMID 32586044, 2020). "The present study investigated whether CAP exerted its anti-obesity effect through changes in the composition of gut microbiota and SCFAs, and whether the TRPV1 contributes to CAP’s effects against obesity in HFD-fed mice." (PMID 32180694, 2020). "These contradictory data indicate the complicated effects of TRPV1 in regulating obesity." (PMID 32175809, 2020). "Moreover, we studied the effect of BCTC, a small molecule TRPV1 antagonist, on oral glucose tolerance in Zucker obese rats, a model of human obesity and insulin resistance." (PMID 31344877, 2019).
Obesity (continued). "EPA (eicosatetraenoic acid) and DHA (docosahexaenoic acid) in fish oil could stimulate the vagus nerve in the intestine through the TRPV1 channels to regulate the development of the sympathetic nerve, thereby reducing the occurrence of obesity." (PMID 31195699, 2019). "First, Trpv1−/− mice were reported to be protected from obesity when kept on HFD." (PMID 31344877, 2019). "These novel findings provide a structural basis for future TRPV1-dependent and TRPV1-independent studies on the primary afferent innervation of PrAT, which may be of interest for the development of future therapeutic obesity and CVD interventions." (PMID 30930754, 2019). "Using transient receptor potential vanilloid 1 knockout (TRPV1−/−) mice, we tested the hypothesis that TRPV1 protects against obesity-induced exacerbation of renal ischemia-reperfusion (I/R) injury." (PMID 30834186, 2019). "In summary, these results suggest that TRPV1 could play a protective role in renal I/R injury in obesity possibly via enhancing renal blood flow through increasing CGRP release." (PMID 30834186, 2019). "These novel findings provide a structural basis for future TRPV1-dependent and TRPV1-independent studies on the sensory innervation of PrAT, which may be of interest for future therapeutic obesity treatment and intervention." (PMID 30930754, 2019). "In this study, we tested the hypothesis that WD intake-induced obesity exacerbates renal I/R recovery and that TRPV1 ablation enhances renal perfusion impairment and subsequently deteriorates the recovery of renal function." (PMID 30834186, 2019). "In addition, TRPV1 appears to be dysregulated in obesity, possibly due to alterations in the interaction with other systems." (PMID 30108548, 2018). "Nonetheless, it is increasingly apparent that TRPV1 may be dysregulated in obesity and contributing to the development of this disease." (PMID 30108548, 2018). "Numerous epidemiology studies and animal studies indicated that capsaicin, as a transient receptor potential vanilloid 1 (TRPV1) agonist, may represent a potential strategy to treat obesity." (PMID 28424369, 2017). "Experimental studies demonstrated that activation of TRPV1 by capsaicin could ameliorate obesity, diabetes, and hypertension." (PMID 27120617, 2016). "The role of the TRPV1 channel deletion in obesity is controversial." (PMID 27120617, 2016). "This shows that TRPV1 stimulation may decrease the number and size of fat cells, thereby preventing the development of adipogenesis and obesity." (PMID 27455231, 2016). "The results from both human and animal studies indicate that TRPV1 and its agonist capsaicin are involved in energy expenditure and may represent a potential strategy to treat obesity." (PMID 27120617, 2016). "Our data are consistent with this issue that targeting TRPV1 is a potential for treating obesity." (PMID 26621679, 2015). "It has been suggested that activation of TRPV1 channels might be a target for the management of obesity." (PMID 26285043, 2015). "Whether TRPV1-evoked alterations in Cx43-mediated adipocyte-to-adipocyte communication play a role in obesity is unknown." (PMID 25849380, 2015). "Given the potentially important role that inflammation plays in the etiology of obesity and metabolic disorders, excessive TRPV1 activity may be involved." (PMID 24798548, 2014). "It is tempting to speculate that increased LC-CoA-mediated TRPV1 channel activation may occur via changes in fatty acid metabolism and transport observed in T2D and obesity where dietary consumption of saturated fatty acids is a contributory factor." (PMID 24798548, 2014). "Collectively these findings suggest that excessive TRPV1 activation may be a contributing mechanism to the development of obesity and T2D." (PMID 24798548, 2014). "Physiological or pathophysiological effects of non-neuronal TRPV1 have been implicated in inflammation, infection and immunity, the cardiovascular system and in conditions such as obesity." (PMID 23800232, 2013).
Obesity (continued). "Therefore, TRPV1 may be a target for the treatment of weight loss disorders, and finding a drug or stimulation method (mechanical stimulation or temperature stimulation) that can treat obesity by acting on TRPV1 will be our next research direction." (PMID 40677717, 2025). "The anti-obesity property of capsaicin has been associated with uncoupling protein (UCP) proteins, which induce activity on energy expenditure and increase thermogenesis, which initially begins with the interaction of capsaicin with TRPV1, initiating the transmission of signals for UCP proteins." (PMID 40559396, 2025). "Several studies have examined the role of transient potential receptor potential vanilloid 1 (TRPV1) channels in obesity using knockout models, and generally indicate that TRPV1 channels differentially contribute to thermogenic and sympathetic regulation in animal models of obesity." (PMID 38510524, 2024). "However, whether the regulatory effect of TRPV1 in adipose tissues plays a role in the occurrence of obesity-related hypertension remains uninvestigated." (PMID 35043013, 2022). "Moreover, it is not easy to reconcile the genetic Trpv1 inactivation studies with the capsaicin desensitization experiments: the first exacerbates aging-associated obesity whereas the second seems to protect against it." (PMID 35890150, 2022). "However, whether the regulatory effect of topical capsaicin on obesity is through TRPV1 to activate central nervous system remains to be further studied." (PMID 34249940, 2021). "Third, activation of TRPV1 may prevent adipogenesis and obesity." (PMID 34229688, 2021). "We conclude that TRPV1 antagonists may represent a class of novel anti-diabetic drugs that regulate hyperglycemia and prevent weight gain by ameliorating the low-grade inflammation that is seen in diabetes and in obesity." (PMID 31344877, 2019). "From these findings, it could be found that the excitability of the sympathetic nervous system could stimulate the opening of TRPV1 channels, which could promote calcium ions influx into adipocytes and enhance the metabolism of brown adipose, thereby decreasing the incidence of obesity." (PMID 31195699, 2019). "Compared with obese rodents or humans, the expression of TRPV1 in lean counterparts is greater in visceral adipose tissues, indicating the expression of TRPV1 in adipocytes may play a role in preventing adipogenesis and obesity." (PMID 27735847, 2016). "Likewise, it has been evidenced the TRPV1 downregulation during adipogenesis of preadipocytes as well as on visceral adipose tissue from db/db and ob/ob mice, suggesting that TRPV1 function prevents adipogenesis and consequently obesity." (PMID 27065858, 2016). "In conclusion, we provided new evidence that TRPV1 activation by dietary capsaicin promotes visceral fat remodeling through the up-regulation of Cx43, which may represent a novel strategy for the management of obesity." (PMID 25849380, 2015). "Thus, fish oil intake can induce UCP1 expression in classical brown and beige adipocytes via the SNS and TRPV1, and may contribute to an effective treatment for obesity." (PMID 26673120, 2015). "TRPV1 channels selectively modulate gastric vagal afferent tension receptor mechanosensitivity and may mediate the reduction in gastric vagal afferent mechanosensitivity in high fat diet-induced obesity." (PMID 26285043, 2015). "Thus the overall effect of TRPV1 modulation in obesity is stark." (PMID 23800232, 2013). "However, while our findings establish CAP as a TRPV1-dependent hepatoprotective agent in diet-induced obesity, it remains unclear whether these effects are mediated solely through systemic metabolic improvements or whether CAP also acts directly on the liver, independent of weight reduction." (PMID 40864772, 2025).